ERBB2 (erb-b2 receptor tyrosine kinase 2)
Diseases named in the same sentence as ERBB2 in open-access papers (continued):
Sharing a sentence is not in itself a finding about the gene and the disease.
tumor (continued). "Our tumor models were slightly different compared to the models published several years ago by other investigators, where the authors used the MMTV-Neu mouse model with Y1144 (YB) and Y1227 (YD) mutation in ErbB2 to activate specific HER2 signaling pathway - Shc or Grb2, respectively." (PMID 25280532, 2014). "However, we feel that tumour ErbB2-IR has limited value as a clinical marker to aid treatment decisions, for three reasons: firstly, its magnitude is limited given that the area under the ROC curve, albeit significant, is a meagre 0.60 (values ≤0.75 have been described as “not clinically useful”)." (PMID 25215939, 2014). "In the context of tumors driven by unregulated ErbB2 signaling, complete loss of LKB1 does not affect the latency of tumor formation driven by the ErbB2 oncogene; rather, it increases the total number of pre-neoplastic lesions and overt tumors that form in these animals." (PMID 24280377, 2013). "Indeed, a large number of oncogenes (e.g., ERBB2, MYCN, KRAS, etc.) are amplified at the level of the genome within various tumor types and this amplification not only underlies hypermorphic expression and/or function, but also serves to differentiate the tumor cells from normal surrounding tissues." (PMID 24202319, 2013). "A hypothesis for this difference in response between these two models is that established ErbB2 tumour cells have become addicted to the requirement for FAK function whereas MMTV-NIC-initiated tumour cells have evolved to circumvent the FAK signalling network through compensation by Pyk2." (PMID 22373082, 2012). "In addition, the FAK-null ErbB2 tumours retained their metastatic potential." (PMID 22373082, 2012). "Similarly, ErbB2-driven tumor cells are EGFR-dependent and also display HGF-mediated rescue." (PMID 23028720, 2012). "Erb-hcAb-RNase could be a promising candidate for the immunotherapy of ErbB2-positive tumours." (PMID 21559015, 2011). "The system of detection of erbB2 in DNA from plasma by real-time PCR is innovative and with the validation in a larger cohort of patients can be used for monitoring the assessment of the extent of tumor dissemination and the potential development of distant metastasis." (PMID 21481261, 2011). "Furthermore, the increased ErbB-2 activity in the luminal A tumours that become resistant to antihormonal therapy may be an important target for alternative or combination therapy that attempts to prevent and/or reverse the resistance to antihormonal therapy." (PMID 21847123, 2011). "Ethanol-stimulated tumor cell/ECM interaction may be initiated by its effect on ErbB2 activity." (PMID 21034468, 2010). "We report that EDIAs are active also on trastuzumab-resistant tumour cells both in vitro and in vivo, most likely because of the different epitope recognised, as EDIAs, unlike trastuzumab, were found to be able to inhibit the signalling pathway downstream of ErbB2." (PMID 20051960, 2010). "However, it remains to be established whether BCAR4-positive primary tumours have elevated levels of phosphorylated ERBB2 or ERBB3." (PMID 20859285, 2010). "EGFR and erb-B2 were expressed in 34% and 17% of the specimens, but the authors could not demonstrate any association between EGFR expression or erbB2, and tumour depth, lymph node status, extracapsular invasion, recurrence, or survival." (PMID 19696947, 2009). "In particular, this hypothesis is supported by the in vitro targeting experiments showing that ALM is capable of selectively binding ErbB2‘+’/ErbB3‘+’ tumour cells when present in a milieu of cells that express either elevated levels of one or normal levels of both target antigens." (PMID 18841159, 2008). "It has recently been demonstrated that another secondary signalling molecule, ShcA, is required for ErbB2-mediated tumourigenesis and phosphorylation of Tyr313 in ShcA may be important for tumour cell survival, while phosphorylation of Tyr239/240 may be important for tumour vascularisation." (PMID 18700973, 2008).
tumor (continued). "Interestingly, in the present study the highest expression levels of cytoplasmic HRGβ1 were found in patients with tumours that expressed high levels of membrane EGFR and increased activity of the EGFR-associated signalling elements, membrane erbB2, nuclear MAPK and nuclear AKT." (PMID 17686159, 2007). "Indeed, subgroup 10 (which includes most of the basal-like tumours) and subgroup 9 (which includes most of the ERBB2 tumours) both exhibited a bad prognosis (with rates of recurrence of 57% and 53%, respectively) in agreement with their higher histological grade (80–100% SBRIII)." (PMID 17338809, 2007). "COX2 contributes to increased anti-apoptotic, pro-angiogenic, and metastatic potential in cancer cells, and deregulation of COX2 expression was associated with tumor progression, suggesting that COX2 overexpression induced by nuclear ErbB2/HER2 in cancer cells may be a marker of bad prognosis." (PMID 17049074, 2006). "Of these, 25 have a mutation frequency above 5% in one or more tumour type while the other three, ERBB2, FGFR2 and SUFU, have biologically plausible mutations but a low mutation frequency (mutation frequencies in all available data are; 1.2% for ERBB2, 2% for FGFR2 and 1.6% for SUFU)." (PMID 16421597, 2006). "Based on these findings, we suggest that P-Akt could play a predictive role with respect to Herceptin, topoisomerase IIα inhibitors and combination therapies using Akt inhibitors, which are currently in clinical trials and should primarily be assessed in patients with ErbB-2-overexpressing tumours." (PMID 15987444, 2005). "Promotion of tumor proliferation through the upregulation of cyclinD1/E1 and downregulation of p21 via the PI3K/AKT and MAPK/ERK pathways in complex with ErbB2." (PMID 40868185, 2025). "Examining tumor samples by IHC, D1SP-treated tumors had lower percentages of Ki-67+ cells and less protein expression of p-ErbB3, p-ErbB2, and p-cMet compared with control tumors." (PMID 39748059, 2025). "Single-cell DNA sequencing revealed heterogeneity of ERBB2 copy number profiles in SMBO-109 organoids, an organoid model with discordance of ERBB2 amplification status between the PDO and tumor from which it was derived." (PMID 41422272, 2025). "Using systems pharmacology, we identified 50 anti‐HCC core targets, including EGFR, c‐Myc, ERBB2, ESR1, CCND1, and HSP90AA1, all of which play critical roles in tumor initiation, proliferation, angiogenesis, and resistance mechanisms." (PMID 40727254, 2025). "To further assess potential on-target, off-tumor effects, we analyzed CD155 expression patterns alongside reference genes (EGFR, ERBB2, and ROR1), which are currently being investigated in clinical trials for CAR-T therapies." (PMID 40478751, 2025). "ERBB2 (HER2), with established significance as a biomarker in multiple tumor types and as the target of an extensive armamentarium of drugs, is exemplary of the critical need for contextualization in the field of precision medicine." (PMID 40178042, 2025). "Next, we tested both CAR-effector cells against primary tumor samples (H1, H9) obtained from relapsed, metastatic pediatric RMS that were confirmed to express ErbB2 via flow cytometry." (PMID 39963129, 2025). "For instance, higher mRNA expression levels of MKI67, ERBB2, and ESR1 have been positively correlated with higher tumor stages and grades, suggesting their potential utility in clinical practice." (PMID 40948378, 2025). "Among patients with both STK11 and KEAP1 wild-type tumours, a low TMB and alterations in the ERBB2 pathway were detected in 66.7% of cases." (PMID 40650126, 2025). "To the end, we demonstrated a novel ERBB2 isoform as a tumor-promoting factor in the development of GBC and deciphered a novel resistance mechanism of anti-ERBB2 treatment." (PMID 39948369, 2025). "In cervical cancer (CCa), GDF15 promotes tumor proliferation by upregulating CyclinD1 and CyclinE1 while downregulating p21 via the PI3K/AKT and MAPK/ERK pathways in conjunction with ErbB2." (PMID 40868185, 2025).
tumor (continued). "ERBB2 blockade alone resulted in a significant increase of activated CD4+ and CD8+ T cells in the tumor." (PMID 41361170, 2025). "In contrast, among patients with both STK11 and KEAP1 wild-type tumours, low TMB and alterations in the ERBB2 pathway were detected in 2/3 of cases." (PMID 40650126, 2025). "Specifically, MKI67 expression showed a strong correlation with tumor grade, while ESR1 and ERBB2 also demonstrated significant differences between various grades and stages." (PMID 40948378, 2025). "EGFR, ERBB2, and FGFR1 are known to promote tumor growth and survival independently of AR signaling." (PMID 40429793, 2025). "Tumor antigens that have been successfully targeted include epidermal growth factor receptor (EGFR), ERBB2, vascular endothelial growth factor (VEGF), cytotoxic T lymphocyte-associated antigen 4 (CTLA4), CD20, CD30 and CD52." (PMID 41294857, 2025). "It is important to note that analysing fast disease progression cases in our research, both patients with STK11 and KEAP1 wild-type tumours had low TMB and harboured ERBB2 alterations (amplification and co-occurring alteration)." (PMID 40650126, 2025). "With pan-tumor approval of HER2-targeted therapies like Trastuzumab deruxetecan (T-DXd), understanding ERBB2 alterations across diverse cancers is crucial." (PMID 40828885, 2025). "In NSG mice xenografted with ErbB2+ RMS, a single injection of either CAR-effector cells strongly impeded metastatic tumor development and significantly improved survival." (PMID 39963129, 2025). "Notably, these mutations can sustain oncogenic signaling and confer resistance to EGFR-targeted therapies, while ERBB2 amplification is linked to a non-inflammatory tumor microenvironment that may impact immunotherapy response." (PMID 40828885, 2025). "Among them, seven cancer genes (ERBB2, ERBB3, PPARG, MYC, CCND1, CCNE1, MDM2) were detected to be amplified in both ctDNA and tumor tissues, indicating the reliability of ctDNA in reflecting the genomic features of tumors." (PMID 40191434, 2025). "This low prevalence is consistent with the need for more robust ERBB2/HER2 testing strategies, particularly in tumor types where HER2 overexpression is less common." (PMID 40828885, 2025). "ERBB2 (HER2) and MET are both well‐established oncogenes that drive tumor growth, survival, and therapy resistance." (PMID 40952239, 2025). "Tumor growth was monitored, and molecular analyses included RNA sequencing and immunofluorescence quantification of PI3K, AKT1, mTOR, ERBB2, BRAF, and MITF protein levels, and molecular docking simulations were performed." (PMID 40806647, 2025). "NGS (YucoOne® Pro+ panel; depth 2134.4×; tumor content 55%) confirmed ERBB2 amplification (copy number 37.3), indicating HER2 heterogeneity from primary (1+) to metastasis (3+)." (PMID 41550934, 2025). "These cells efficiently lysed ERBB2-positive RMS cells in vitro and significantly suppressed tumor progression in a metastatic xenograft model." (PMID 40508013, 2025). "Immunohistochemical analysis showed strong, complete membrane staining for HER2/neu oncoprotein in invasive ductal carcinoma cells, with over 10% of tumor cells assigned a HER2/neu score of + 3, reflecting ERBB2 gene amplification." (PMID 41403731, 2025). "Our findings provide important insight into unmet therapeutic needs for patients with cancers harboring ERBB2/ERBB3 alterations, which is essential for a new paradigm of pan-tumor HER2-targeted therapy." (PMID 40178042, 2025). "The low prevalence of ERBB2 and ERBB3 activating alterations across a variety of tumor types supports a tumor agnostic approach to investigations." (PMID 40178042, 2025).
tumor (continued). "GDF15 promotes tumor cell proliferation and invasion by upregulating STAT3 phosphorylation or by activating ErbB2, which is central to the PI3K/AKT and mitogen-activated protein kinase (MAPK) pathways." (PMID 40868185, 2025). "Drugs targeting ERBB2, such as EGFR inhibitors, effectively block this signaling pathway, thus inhibiting tumor cell growth and proliferation." (PMID 40170854, 2025). "This complex stimulates the PI3K pathway, thereby enhancing the secretion of MUC4 mucin within tumor cells; MUC4, in turn, activates ErbB2, forming a sustained positive feedback loop involving the ErbB2/ErbB3-MUC4 axis." (PMID 41310663, 2025). "HER2-enriched BCs are characterized by the amplification and overexpression of the HER2/ERBB2 gene, which drives aggressive tumor behavior." (PMID 41011238, 2025). "While dabrafenib directly inhibits BRAF activity, HT induced a broader suppression of oncogenic proteins involved in tumor-stroma crosstalk and angiogenesis, including VEGFR-2, WIF-1, ITGB5, and ERBB2/3/4." (PMID 40725203, 2025). "For instance, Listeria monocytogenes and F. nucleatum can activate RTKs like ErbB2, ErbB3, and EGFR, promoting tumor growth and resistance to RTK-targeted therapies in CRC." (PMID 39948481, 2025). "Epidermal growth factor receptor (EGFR/ErbB1/HER1) and other members of the ErbB family, including ErbB2/HER2, ErbB3/HER3, and ErbB4/HER4, are receptor tyrosine kinases that play critical roles in tumor progression across various types of cancer." (PMID 40445424, 2025). "In contrast, ERBB2, SDC1, and MMP14 exhibited elevated expression levels in the tumor group (All p < 0.05)." (PMID 38189813, 2024). "In multivariable analysis of high ERBB2 expressing tumors, increase in DUSP6 expression and large tumor size (T4) remained significant independent prognostic factors." (PMID 38886591, 2024). "Our data analysis identified ERBB2 as a direct regulator of key oncogenes such as MYC and BCL2, and tumor suppressors like PTEN in several cancers including PC." (PMID 39409883, 2024). "The expressions of CyclinE1, ERBB2, and ENO1 in the tumor were inhibited by PP in vivo, consistent with that observed in vitro." (PMID 39576845, 2024). "ERBB2 AMP and concomitant genetic alterations detected through the targeted tumour sequencing test are potential indicators of treatment response to trastuzumab therapy." (PMID 38862927, 2024). "While there is no recurrent gene amplification that was observed, the following genes were amplified in two tumor samples: MET, SMO, ERBB2, BRAF, EZH2, SRSF2, CUX1, and CEBPA." (PMID 38164123, 2024). "Multiregion sequencing of the primary tumor and metastatic sites revealed differences in the genomic profiling, including oncogene amplifications such as EGFR, ERBB2, MET and PIK3CA." (PMID 38611014, 2024). "We found that CHST2 and the well-known target genes of the proposed drugs, HRH1, and EGFR/ERBB2, were co-expressed in the GBM tumours as shown in iNetModels." (PMID 39063109, 2024). "Higher histological grade, higher tumor stage, and more frequent nodal involvement significantly distinguish ERBB2‐amplified ILBC from ERBB2‐unamplified ILBC." (PMID 38335502, 2024). "In summary, the involvement of NRG1 in promoting ERBB3-mediated signaling and the formation of oncogenic heterodimers with ERBB1, ERBB2, and ERBB4 highlights the significance of NRG1 fusions in driving abnormal cell proliferation and tumor progression." (PMID 38957319, 2024). "By modifying the criteria for measuring gene copy numbers and considering tumor characteristics, this study aimed to enhance the accuracy of amplicon-based NGS in detecting gene amplifications with a specific focus on ERBB2 gene amplification." (PMID 39682116, 2024). "Based on this mechanism, one of the anticancer mechanisms of ALA involves reducing tumor cell activity at the TKR level and inhibiting tumor cell proliferation mediated by the oncogenes ERBB1/EGFR and ERBB2/HER2." (PMID 39199143, 2024).
tumor (continued). "ERBB2 CNA was compared to HER2 status evaluated by IHC/FISH in FFPE block sections, which were identical to those subjected to the targeted tumour sequencing test." (PMID 38862927, 2024). "More encouraging are the recently developed anti-ERBB/ERBB2/ERBB3 targeted therapies for the treatment of carcinomas harboring NRG1 fusions, as would be considered for our patient if her tumor were to eventually recur." (PMID 39575425, 2024). "We have elucidated the role of FOXM1 in regulating cellular proliferation and tumor growth in EAC patient-derived organoids and cell lines and identified ERBB2 signaling as an upstream regulator of FOXM1." (PMID 38373993, 2024). "Drugs targeting the binding of NRG1 to ERBB3 and/or the heterodimerization of ERBB2/ERBB3, such as the bispecific monoclonal antibody zenocutuzumab, have demonstrated tumor volume reduction inNRG1fusion-positive tumors." (PMID 38414979, 2024). "In summary, we found significant CNA differences in CDKN2A, ERBB2, SMAD4, and CCNE1 between pNET and sbNET tumor samples after combined analyses of chromosomal microarrays, RNA sequencing, and fluorescence in situ hybridization data." (PMID 39062773, 2024). "Using an ErbB2+ Genetically Engineered Mouse Model (GEMM), we show that Cpt1a ablation delays tumor onset in ErbB2+ tumors, reducing both angiogenesis and metastatic capacity." (PMID 39097623, 2024). "Initial analyses revealed that mRNA expression of ITGB6, ERBB2, RAB5A, RAB7A, and GDI2 was all significantly higher in tumor tissue in comparison to normal tissue." (PMID 39630893, 2024). "Our results indicate that by taking tumor cellularity into account, the CN cut-off can be adjusted to below four, thereby maximizing the performance of NGS assays for detecting ERBB2 gene amplification." (PMID 39682116, 2024). "Similar to the Erbb2 model, to control for unanticipated effects of TAM on tumor growth, we also examined tumor growth in K-rasLA1/Cre/Pfkfb3+/+ mice (WT for Pfkfb3) administered vehicle ± TAM and found similar growth in both groups." (PMID 39001392, 2024). "To investigate the clinical relevance of ERBB2, we used UALCAN to analyze the expression of ERBB2 in HCC tumor tissues compared to normal tissues." (PMID 37324014, 2023). "In this study, the serum levels of ERBB2 and NRG4, which are involved in the EGFR signaling pathway, correlated with tumor characteristics." (PMID 37174100, 2023). "By contrast, tumours with a lower TMB, WNT pathway, CDH1, JAK2, ERBB2 and FGFR2 alterations as well as terminally differentiated exhausted CD8+ T-cells were pembrolizumab-insensitive." (PMID 37370858, 2023). "Co‐overexpression of the PGAP3 and ERBB2 was correlated with T stage, TNM stage, tumour size, intestinal histological type and poor survival proportion in 141 GC patients." (PMID 37386793, 2023). "On day 36, we randomized the mice into five different groups, namely, wildtype, vector, desARE3’UTR ERBB2-1, desARE3’UTR ERBB2-3, and desARE3’UTR ERBB2-30 with the groups having equal representation of tumor size." (PMID 37359373, 2023). "We initially compared the total expression levels of ERBB2, RAD21, RAD50 and BARD1 mRNA in normal and tumor bladder tissues with bioinformatics analyses using the TCGA database (Cohort one)." (PMID 37474724, 2023). "The organism is a complex regulatory process, and proteins or transcription factors such as ErbB2 and BACH1, which are involved in tumor development, also have positive/negative regulation on HK II." (PMID 38202657, 2023). "Given the links we uncovered between ERBB2 signalling and AP-1 in our cell line models, we sought evidence for elevated AP-1 activity in OAC patients with tumours containing ERBB2 amplifications." (PMID 36694726, 2023).